IGF1 (insulin like growth factor 1)
Diseases named in the same sentence as IGF1 in open-access papers (continued):
Sharing a sentence is not in itself a finding about the gene and the disease.
acromegaly (continued). "The systemic effects of acromegaly, including cardiovascular, respiratory, metabolic, and neurologic complications, lead to elevated mortality in these patients, which should be managed by suppressing GH and IGF-1 levels to that of the normal population." (PMID 37755395, 2023). "However, we reveal a negative correlation between fasting GH and the FokI ff genotype in all acromegaly groups and with IGF-1 levels in the cured disease group." (PMID 37446150, 2023). "Interestingly, rosiglitazone reduced the levels of growth hormone (GH) and insulin-like growth factor 1 (IGF-1) in patients with acromegaly and promoted apoptosis and autophagy in primary somatotroph adenoma and GH3 cells." (PMID 37250410, 2023). "Thus, consensus on acromegaly management recommended to wait at least 12 weeks after surgery to assess IGF-1 levels, as the postoperative decline in IGF-1 levels can be delayed compared with that of GH levels." (PMID 37829686, 2023). "Somatostatin analogs preferentially bind to somatostatin receptors SST2 and SST5, suppressing growth hormone (GH) secretion, effectively controlling the biochemical parameters of acromegaly in 60 to 80% of patients (normal values of insulin-like growth factor 1 (IGF-1) and GH < 1 μg/L)." (PMID 35913681, 2023). "IGF-1 was an independent predictor of inter-AEMD in patients with acromegaly." (PMID 37959322, 2023). "In summary, most recent studies and observation states that hypercalcemia in acromegaly results from the overproduction of GH and IGF-1, and furthermore, the activation of numerous mechanisms, which the dominant one seems to be an increase of the 1,25-dihydroxyvitamin D concentration." (PMID 37373574, 2023). "The clinical manifestations of acromegaly are due to an excess of GH and IGF-1." (PMID 37842314, 2023). "Sustained exposure to increased levels of IGF-1 may have a role in the occurrence of thyroid nodules and elevated IGF-1 levels are related to the presence of thyroid nodules in patients with acromegaly." (PMID 36945936, 2023). "The aim of our study was to determine the relationship of four FTO gene polymorphisms (rs1121980, rs1421085, rs9930506, rs9939609) with selected parameters of lipid and glucose metabolism as well as with IGF-1 and GH levels in the group of patients with acromegaly compared to the control group." (PMID 37446150, 2023). "Mean IGF-1 level in acromegaly patients was 308 ± 247 ng/ml with a GH of 3.54 ± 6.23 ng/ml." (PMID 36309947, 2023). "In fact, remission of acromegaly is usually assessed 3 months after neurosurgery, when IGF-1 levels stabilize, but long-term biochemical control could be reached several years after initial surgery." (PMID 37829686, 2023). "In acromegaly, log GH concentrations are directly correlated with IGF-1 concentrations." (PMID 37762211, 2023). "Increased RA minor diameter could be detected in acromegaly, which correlated with hGH and IGF-1 levels." (PMID 37959322, 2023). "Meanwhile, Clotho, a potent inhibitor of both IR and IGF-1R via interruption of their tyrosine phosphorylation, has been recently found to be increased in acromegaly, thus, it may also contribute to IGF-1 resistance." (PMID 36882643, 2023). "As a result, PEGV is the best medication for controlling IGF-1 in acromegaly." (PMID 37762211, 2023). "Notably, in the analysis of the overall acromegaly cohort in our center, differences between the most recent GH, IGF-1, and remission rates were less significant than in the case-control section." (PMID 37442901, 2023). "Acromegaly is a chronic neuroendocrine disorder primarily attributed to pituitary neuroendocrine tumors (PitNETs) secreting growth hormone (GH), thereby prompting excessive production of insulin-like growth factor 1 (IGF-1)." (PMID 37929035, 2023). "IGF-1 levels are correlated with thyroid volume in patients with acromegaly." (PMID 36945936, 2023).
acromegaly (continued). "Based on the criteria above, our patient could be diagnosed with subclinical acromegaly, with initial IGF-1 level being 1.6-fold greater than the ULN, having enlargement of the feet, prediabetes, and a pituitary adenoma." (PMID 37543629, 2023). "The aim of the study was to determine the relationship of risk alleles of four FTO gene polymorphisms with selected parameters of lipid and glucose metabolism as well as with IGF-1 and GH levels in the group of patients with acromegaly compared to the control group." (PMID 37446150, 2023). "Only few studies exist exploring systemic effects of GH and IGF-1 in patients with acromegaly." (PMID 36508085, 2023). "Life expectancy in patients with acromegaly are affected by the biochemical control of IGF-1." (PMID 37373801, 2023). "The primary screening test for the diagnosis of acromegaly is the measurement of IGF-1 levels." (PMID 37373574, 2023). "Functional tumors cause conditions related to hormonal hypersecretion, such as elevated plasma growth hormone (GH) and/or insulin-like growth factor 1 (IGF-1), leading to acromegaly and inappropriate secretion of thyroid stimulating hormone (TSH), causing central hyperthyroidism." (PMID 37324275, 2023). "Screening for acromegaly can be accomplished by serum measurement of IGF-1." (PMID 36721176, 2023). "Notably, following treatment for acromegaly, a resolution of polycystic morphology of the ovaries and normalization of menstrual cyclicity has been described, suggesting a direct link between IGF-1 and the PCOS phenotype." (PMID 36721176, 2023). "Levels of IGF-1, which is a hormone produced by the liver in response to GH stimulation, are also increased in acromegaly and IGF-1 may have direct effects on the ovaries." (PMID 36721176, 2023). "Insulin and IGF-1 serum levels may be elevated in the course of many endocrine disorders, including acromegaly, hyperprolactinemia, hypercortisolism, or congenital adrenal hyperplasia." (PMID 37626790, 2023). "This may have been due to the lipolytic and insulin resistance effects of GH and IGF-1, which results in the mobilization of free fatty acids and the resistance of blood glucose found in acromegaly patients." (PMID 37886642, 2023). "Few studies have analyzed the spectrum of available treatments for managing GH and IGF-1 levels in acromegaly, focusing on the efficacy, safety, and patient satisfaction of treatment with octreotide capsules (Mycapssa®) across multiple clinical trials and open-label extensions of these trials." (PMID 37755395, 2023). "Screening for acromegaly is often performed by measuring random GH concentrations and IGF-1." (PMID 37762211, 2023). "Therefore, both GH-induced hyperinsulinism and elevated IGF-1 levels are likely contributors to the hyperandrogenic state in acromegaly resulting in clinical signs/symptoms quite similar to those of PCOS." (PMID 36721176, 2023). "In addition, a multivariate analysis showed that AH and IGF-1 levels were determinants of LV hypertrophy in acromegaly." (PMID 36309947, 2023). "Combining that random fasting GH is probably a poor predictor of IGF-1 in acromegaly, IGF-1 (especially ULN) was more stable and might be more likely to reflect the risk of cancers in acromegaly." (PMID 37442901, 2023). "Similarly, GH was reported to influence corneal thickness in conditions of excess IGF-1 production post-pubescent, such as acromegaly, resulting in a ~3–7% increase in corneal thickness." (PMID 35053340, 2022). "Based on this evidence, the disruption of GH/IGF1 axis occurring in acromegaly might represent per se a pathophysiologic mechanism responsible for cognitive impairment in acromegaly patients." (PMID 36165745, 2022). "Also, serum GH (1.39 (3.37–0.55) vs. 0.32 (0.78–0.09); p < 0.001) and IGF-1 (249.9 ± 189.3 ng/mL vs. 147.1 ± 39.6 ng/m; p = 0.009) levels were significantly higher in patients with acromegaly." (PMID 36326330, 2022).
acromegaly (continued). "Whether such cognitive decline in acromegaly is a result of excessive secretion of GH and IGF-1 remains to be elucidated." (PMID 36505847, 2022). "The exact role of IGF-1 in pathology of CTS in acromegaly remains uncertain." (PMID 36277124, 2022). "Acromegaly, because of chronic overproduction of IGF-1 levels, was present in 18 (16.5%) cases." (PMID 36498723, 2022). "In acromegaly, the excess of growth hormone (GH) and insulin-like growth factor 1 (IGF-I) induces a specific cardiomyopathy whose most common feature is concentric hypertrophy, usually associated with diastolic dysfunction and eventual impairment of systolic function and HF." (PMID 34318387, 2022). "In addition to therapies targeting GH and IGF-1 oversecretion, patients often require treatment for acromegaly-related comorbidities, resulting in prescription of multiple medications." (PMID 34973139, 2022). "Acromegaly diagnosis is predicated upon blood measurements of GH and IGF-1." (PMID 35992136, 2022). "The acromegaly phenotype was described well before GH/IGF-1 were isolated and described." (PMID 35992136, 2022). "Here, we demonstrate that CMBs exist in patients with acromegaly with a higher prevalence of about 29.09% than in HCs, which suggests an injury of the cerebral small vessel after persistent exposure to excess GH and IGF-1 levels." (PMID 36505847, 2022). "Acromegaly is usually confirmed by an increase in blood insulin-like growth factor-1 (IGF-1)." (PMID 38983521, 2022). "In acromegaly, IGF1 usually remains stable throughout the remaining period of gestation time because of the estrogen-induced state of GH resistance that prevents somatotropinoma-associated production of pituitary GH to have clinical and metabolic fetal consequences." (PMID 36359512, 2022). "Acromegaly is an endocrine disorder characterized by dysregulated hypersecretion of growth hormone (GH), leading to an overproduction of insulin-like growth factor 1 (IGF-1)." (PMID 36105896, 2022). "It is known that increased GH and IGF-1 levels play a role in all complications in acromegaly." (PMID 35340319, 2022). "The long term exposure to GH and IGF-1 in acromegaly may be due both to the persistence of active disease and both to the diagnostic delay." (PMID 35922724, 2022). "When acromegaly is suspected in patients with classical clinical signs and symptoms, especially acral and facial features, the ES guidelines recommend measuring IGF-1 levels." (PMID 36105896, 2022). "Sensitivity analysis by excluding those with acromegaly did not change the relationship between IGF-1 and the risk of IVS thickening." (PMID 36568107, 2022). "It is known that increased GH and IGF-1 levels affect bone turnover in patients with acromegaly." (PMID 35340319, 2022). "However, patients with acromegaly had higher GH (8.05 ± 16.18 vs. 0.78 ± 1.25 ng/mL) and IGF-1 (547.0 ± 342.1 vs. 146.7 ± 51.4 ng/mL) levels than in subjects with IFG." (PMID 35248150, 2022). "Our data can suggest a cumulative effect over time of the GH and IGF-1 hypersecretion on bone homeostasis, possibly explaining the effect of acromegaly diagnostic delay on the incidence of VFs rather than on their prevalence." (PMID 35922724, 2022). "Regarding clinical and imaging predictors of medical treatment outcome in acromegaly, the most recent data shows, that older age, higher IGF-1 concentration at diagnosis and hypointense T2-weighted MRI signal increase the chance of better response to first-generation SRLs." (PMID 36187106, 2022). "IGF-1’s insulin agonism may partially offset those of GH, but circulating IGF-1 has a little role in regulating glucose homeostasis in acromegaly." (PMID 36176462, 2022). "Furthermore, both GH and IGF-1 have been described as predictive markers for surgical outcome in acromegaly along with tumor volume and cavernous sinus invasion." (PMID 36042253, 2022).
acromegaly (continued). "Acromegaly, mostly due to a somatotroph pituitary adenoma, is an endocrine and metabolic disease characterized by chronic exposure to excess growth hormone (GH) and insulin-like growth factor 1 (IGF-1) levels." (PMID 36505847, 2022). "The prevalence of glucose metabolism abnormalities in acromegaly varies considerably across different studies, but the prevalence of DM is estimated at 16–56%; additionally, a positive correlation between baseline IGF-1 level and DM was found." (PMID 34498217, 2022). "In addition, a GH nadir during an oral glucose tolerance test (with 75 g glucose administered) < 1 μg/L and normal IGF-1 exclude acromegaly." (PMID 35992136, 2022). "The results of our observational study were consistent with those obtained from clinical trials, or they even can be a proof of higher effectiveness, as the older criterium for biochemical acromegaly control (GH < 2.5 ug/mL and IGF-1 < 1 × ULN) was used in other trials." (PMID 34498217, 2022). "Available literature on sclerostin levels during active acromegaly also reports contradictory data, showing inconsistent associations between sclerostin and GH/IGF-1 levels, ranging from positive to negative correlations." (PMID 34448099, 2022). "In clinical practice, acromegaly is pharmacologically treated by dose titration of somatostatin agonists where the goal is to maximize the suppression of GH secretion at the pituitary somatotrophs, which results in suppression of serum IGF-1." (PMID 35000098, 2022). "Therefore, it is not excluded that SSA treatment in the study patient #5 stabilized the serum IGF-1 levels and prevented the appearance of acromegaly." (PMID 35696052, 2022). "The distinct treatment patterns observed between nations may at least in part be explained by differences of acromegaly cases at baseline between countries, e.g., in IGF-1 level at baseline, as well as by a different treatment history before pegvisomant start." (PMID 35359232, 2022). "Therefore, the goal for treatment of acromegaly is to identify a dose range that results in maximal suppression of GH and IGF-1 by achieving trough concentrations that are at the EC80 or higher." (PMID 35000098, 2022). "Among the typical features of hypogonadism such as decreased libido end Erectile Dysfunction (ED), gynecomastia could arise in acromegaly due to the stimulation of GH and IGF-1 on the mammary gland, as demonstrated on aging primates." (PMID 35364803, 2022). "Acromegaly is a rare systemic pathology (incidence 2–11 cases/million/year) characterized by a chronic hypersecretion of Growth Hormone (GH) and consequently of its peripheral "effector" Insulin-like Growth Factor-1 (IGF-1)." (PMID 35364803, 2022). "Acromegaly is characterized by typical clinical phenotypic and laboratory findings, comprising mainly of elevated growth hormone (GH) levels that are non-suppressible by oral glucose as well as elevated insulin-like growth factor 1 (IGF-1) serum levels." (PMID 36042253, 2022). "Similarly, in acromegaly, IR is a key contributing factor to AN, and possibly excessive amounts of growth hormone (GH) and IGF1 as well." (PMID 36292208, 2022). "In addition, a large proportion of patients biochemically controlled (insulin-like growth factor I (IGF1) ≤ 1.3 × upper limit of normal (ULN)) on injectable SRLs report persistent acromegaly symptoms that interfere with their daily lives." (PMID 36173649, 2022). "Clinically, not only dental components are modified by GH and IGF-1 excess but also soft tissue may be involved in facial changes due to acromegaly." (PMID 35207363, 2022). "In acromegaly, however, excesses of GH and IGF-1 markedly alter these processes." (PMID 36176462, 2022). "However, recent studies reported that skeletal fragility in acromegaly cannot solely be explained by alterations in bone mass, but is mainly the consequence of GH/IGF-1-induced alternations in bone microstructure that impair bone quality." (PMID 34448099, 2022).
acromegaly (continued). "However, patients with acromegaly sometimes have normal oGTT GH suppression despite elevated IGF-1 levels." (PMID 36042253, 2022). "Notably, patients with acromegaly were younger, predominantly men, taller, heavier, with a higher BMI and higher GH and IGF-1 levels." (PMID 35248150, 2022). "We did not observe any correlations between hematological parameters and GH, IGF-1 concentrations in patients with acromegaly when analyzed as a single group which may result from the small sample size." (PMID 34501445, 2021). "Despite the impacts of genetic, familial, and environmental risk factors on type 2 DM occurrence, it is known that DM in acromegaly develops as a result of the effects of GH and IGF-1 excess on the pancreatic β-cell function, insulin sensitivity, and gluconeogenesis." (PMID 34217172, 2021). "A serum insulin-like growth factor 1 (IGF-1) should be obtained to screen for suspected acromegaly." (PMID 34557164, 2021). "The evaluation of IGF-1 is recommended as a screening test for acromegaly." (PMID 34081617, 2021). "In a study of 17 subjects (15 men, 2 postmenopausal women) with acromegaly whose IGF-1 levels remained elevated despite conventional, GH-lowering medical therapy, the addition of tamoxifen reduced IGF-1 levels by an average of 90 ng/mL and normalized plasma IGF-1 in 47% of subjects." (PMID 33910628, 2021). "The clinical overlap between acromegaly in the elderly and physiological aging could be partly explained by a reduced rate of IGF-1 secretion, as was observed in our cohort." (PMID 32840821, 2021). "On the contrary, some cases of low GH acromegaly show low GH levels in the blood but present clinical symptoms, whereas IGF-1 levels in the blood may be low in those with a low nutritional status, liver disorders, and poorly controlled diabetes mellitus." (PMID 33881731, 2021). "IGF-1 is responsible for the majority of the pathological changes that take place in acromegaly." (PMID 34987906, 2021). "Besides the suspicion of acromegaly, IGF-1 levels are often measured in other clinical contexts, as in the presence of incidentally discovered pituitary neoplasms." (PMID 34081617, 2021). "In addition, we also investigated the potential relationships between serum excess GH/IGF-1 levels and microstructural pathological changes in acromegaly." (PMID 33912457, 2021). "In patients with persistent postoperative acromegaly, adjuvant therapy options are needed and may include continuous and often lifelong medical therapy with IGF-1-lowering drugs as well as radiotherapy such as fractionated radiotherapy or radiosurgery." (PMID 33572555, 2021). "GH and IGF-1 levels are used as biomarkers in the diagnosis and follow-up of acromegaly." (PMID 34013701, 2021). "High levels of IGF-1 are responsible for most of the clinical manifestations of acromegaly." (PMID 33803429, 2021). "With this aim we examined the evolution of clinical parameters, GH/IGF-1 secretion and tumour mass after a very long-term drug discontinuation in a series of selected patients with acromegaly characterized by an optimal disease control during chronic treatment with different long-acting SAs." (PMID 34018167, 2021). "Several studies concerning the involvement of miRNAs in regulating the GH/IGF1 axis and the IGF system have been conducted in GH-secreting pituitary adenomas, which are characterized by GH hypersecretion and lead to gigantism in children and acromegaly in adults." (PMID 34484116, 2021). "Biochemical control of acromegaly, as measured by GH and IGF-1 levels, was also assessed." (PMID 33776927, 2021). "In addition to side effects of treatment, acromegaly patients often still experience disease symptoms even when therapy is successful in controlling GH and IGF-1 levels." (PMID 33790860, 2021). "Despite achieving biomedical control, as defined by IGF-1 and GH levels, acromegaly symptoms may persist in many patients." (PMID 33790860, 2021).